KAT6B (lysine acetyltransferase 6B)
Diseases named in the same sentence as KAT6B in open-access papers (continued):
Sharing a sentence is not in itself a finding about the gene and the disease.
glioma (continued). "KAT6B may be applied as a potential therapeutic target for glioma." (PMID 35432536, 2022). "The CNVs for the other four LARs–KAT6B (10q), SIRT1(10q), HDAC10 (22q), and HDAC9 (7q)–were highly associated with the risk signature and may be affected in chromosomal alterations such as 10q−, 22q− and 7+ in gliomas." (PMID 33718432, 2021). "Conversely, overexpression of KAT6B suppresses erastin-induced lipid ROS and ferroptosis in these cells and deletion of STAT3 reverses KAT6B-mediated glioma cell ferroptosis." (PMID 41457120, 2025). "Next, we validated the correlation of KAT6B and STAT3 in the regulation of glioma cells." (PMID 35432536, 2022).
developmental delay (5 papers, 2020 to 2024). "Herein, we are going to report a 14-year-old developmental delay boy with cognitive impairment, significant facial dysmorphisms, undescended testes and bilateral hypoplasis of patellae as a new case of SBBYSS in Iranian population, which is caused by de novo mutation in KAT6B gene." (PMID 38178270, 2024).
Noonan syndrome (5 papers, 2015 to 2025). Noonan Syndrome (NS) is characterized by short stature, typical facial dysmorphism and congenital heart defects. "Noonan syndrome is associated with a translocation that interrupts intron 3 of KAT6B, which can result in KAT6B haploinsufficiency and a reduction of global H3 acetylation." (PMID 41357671, 2025). "Genetic haploinsufficiency of KAT6B was identified in a patient witha Noonan syndrome-like phenotype with reduced H3 acetylation, though this isnot the typical genetic mutation associated with the syndrome." (PMID 39958699, 2024). "Noonan syndrome-like is caused by a group of genes other than the common ones for NS, including mutations in A2ML1, CBL, MAP3K8, MYST4/KAT6B, RRAS and SPRY1." (PMID 34229750, 2021). "Disruption of Kat6b also leads to a Noonan syndrome-like phenotype and hyperactivated MAPK signaling in both humans and mice." (PMID 29977151, 2018). "KAT6B mutations have been shown to predominantly correlate with GPS and SBBYSS, as well as other phenotypic spectra of neurodevelopmental syndromes, such as Noonan syndrome (OMIM #163950), and syndromic craniosynostosis." (PMID 41357671, 2025). "Specifically, such KAT6B alternation enhanced phosphorylation of MEK1/2, ERK, and AKT, which could be reversed when transfecting a high‐expressing KAT6B construct to cells derived from patients with Noonan syndrome." (PMID 41357671, 2025). "Homozygous deletion ofQuerkopf, the mouse homolog of human KAT6B, results in craniofacialabnormalities and defects in central nervous system development inmice,resembling human phenotypes such as growth retardation, facial dysmorphism,and brain anomalies seen in Noonan syndrome." (PMID 39958699, 2024).
sarcoma (5 papers, 2017 to 2025). A usually aggressive malignant neoplasm of the soft tissue or bone. "The differential diagnosis of sarcomas with KAT6B/A::KANSL1 fusion showing low-grade features mainly includes tumors with endometrial stromal or smooth muscle differentiation." (PMID 39627614, 2025). "Since they were originally described, another study reported a series of 12 patients with tumors classified as sarcomas with KAT6B/A::KANSL1 fusion." (PMID 39627614, 2025). "The expression of WT1 seems to be at most focal and weak in most sarcomas with KAT6B/A::KANSL1 fusion, and 50% of the analyzed cases were entirely negative, which would be unusual for LG-ESS." (PMID 39627614, 2025). "In another recent study, the authors focused on methylation profiling and copy number alterations in 18 sarcomas with KAT6B/A::KANSL1 fusion." (PMID 39627614, 2025). "The correct diagnosis of sarcoma with KAT6B/A::KANSL1 fusion is of utmost importance, given that these tumors tend to behave aggressively even in cases which exhibit deceptively bland morphology." (PMID 39627614, 2025). "KAT6B/A::KANSL1 fusion sarcoma is a recently recognized and distinct subtype of uterine sarcoma defined by a characteristic gene fusion involving KAT6B or, less commonly, KAT6A and KANSL1." (PMID 41463261, 2025). "The morphology of sarcomas with KAT6B/A::KANSL1 fusion is variable, but almost all cases exhibited some features suggestive of endometrial stromal differentiation (fibroblastic or fibromyxoid) or hybrid features between endometrial stromal and smooth muscle differentiation." (PMID 39627614, 2025). "According to the current knowledge, due to the overlapping features between endometrial stromal and smooth muscle differentiation, sarcomas with the KAT6B/A::KANSL1 fusion cannot be diagnosed based only on the morphological and immunohistochemical features, and molecular testing is needed." (PMID 39836188, 2025). "Moreover, recently described sarcomas with the KAT6B/A::KANSL1 fusion usually have overlapping features between LG-ESS/endometrial stromal nodule (ESN) and smooth muscle tumors." (PMID 39836188, 2025). "Indeed, we observe two homozygous deletions in lung cancer, but also two homozygous deletions each in liver cancer and sarcoma, suggesting KAT6B may function as a tumour suppressor in multiple cancer types." (PMID 29089486, 2017). "In comparison, none of the 7 out of 8 patients with tumors in the core KAT6B/A::KANSL1 sarcoma cluster, where follow-up was available, died from disease." (PMID 39392508, 2024).
periodontitis (4 papers, 2022 to 2025). An acute or chronic inflammatory process that affects the tissues that surround and support the teeth. "In periodontitis, long-standing inflammation has been shown to induce ER stress via lysine acetyltransferase 6B." (PMID 35844512, 2022).
small cell lung carcinoma (4 papers, 2021 to 2025). Small cell lung cancer (SCLC) is a highly aggressive malignant neoplasm, accounting for 10-15% of lung cancer cases, characterized byrapid growth, and early metastasis. "KAT6B functions as a tumor suppressor to modulate histone H3 lysine 23 acetylation in genomic loss in small cell lung cancer." (PMID 35432536, 2022). "In a similar trend, KAT6B inhibition in small cell lung cancer (SCLC) resulted in accelerated tumor growth, proliferation, and progression." (PMID 41357671, 2025). "The inhibitor of human lysine acetyltransferase KAT6B presents a treatment for small cell lung cancer." (PMID 33500332, 2021). "Furthermore, the depletion of acetyltransferase KAT6B in small cell lung cancer (SCLC) enhances cancer growth in vitro and in vivo, while its restoration inhibits cell growth and formation of metastases." (PMID 39456765, 2024).
Uterine leiomyoma (4 papers, 2015 to 2024). The presence of a leiomyoma of the uterus. "This was followed by case reports describing a rapidly enlarging KAT6B::KANSL1 uterine leiomyoma in a postmenopausal woman and a uterine leiomyosarcoma harboring a KAT6B::KANSL1 gene fusion." (PMID 39392508, 2024). "Prior studies of uterine leiomyomas have identified KAT6B (previously MORF) rearrangements in uterine leiomyomas, but this case is the first to identify a KAT6B-KANSL1 gene fusion in a uterine leiomyoma." (PMID 31027501, 2019). "The breakpoint in 10q22.3 disrupted the KAT6B gene within intron 3 after the first coding exon, i.e., the same intron in which the breakpoint was mapped in four uterine leiomyomas with rearrangement of the KAT6B gene." (PMID 25621995, 2015). "KAT6B was reported to be targeted in four uterine leiomyomas with a chromosome rearrangement involving 10q22 and 17q21–24 and the breakpoint was mapped to the third intron of the KAT6B gene." (PMID 25621995, 2015).
cognitive deficits (3 papers, 2024 to 2025). "Identification of KAT6B as promoting the expression of brain-specific genes in the developing cortex is consistent with the cognitive disorders caused by heterozygous mutations in the human KAT6B gene." (PMID 39537341, 2025). "It is also possible that the reduced anxiety observed in Kat6b+/– mice is due to a broader cognitive impairment, such that these mice may fail to recognize the risks associated with open areas." (PMID 38557491, 2024).
craniosynostosis (3 papers, 2017 to 2023). Craniosynostosis is defined as the premature fusion of one or more cranial sutures leading to secondary distortion of skull shape resulting in skull deformities with a variable presentation. "Not by chance, de novo truncating mutations in KAT6B, which cause a spectrum of disorders, include, although rarely, C1M, and more frequently craniosynostosis which in turn may cause Chiari malformation." (PMID 33337535, 2021).
Say-Barber-Biesecker-Young-Simpson syndrome (3 papers, 2020 to 2024). "The heterozygous mutation of the KAT6B gene can cause SBBYSS (Say-Barber-Biesecker-Young-Simpson syndrome), a rare form of mental retardation and related syndromes, which is mainly manifested as severe mental retardation, special facial features, bone and genital abnormalities." (PMID 32448279, 2020). "Because of clinical overlap between GPS and SBBYSS syndromes, the KAT6B-related disease spectrum is a subject of interest to researchers." (PMID 38178270, 2024).
tongue squamous cell carcinoma (3 papers, 2018 to 2025). A squamous cell carcinoma that arises from the tongue. "miR-22/KAT6B axis serves as a chemotherapeutic regulator by the modulation of PI3k/Akt/NF-κB signaling in tongue squamous cell carcinoma." (PMID 35432536, 2022).
Uterine sarcomas (3 papers, 2024 to 2025). "Uterine sarcomas with KAT6B/A::KANSL1 fusion represent a new entity characterized by bland morphology, commonly with hybrid features of low-grade endometrial stromal sarcoma (LG-ESS) and tumors with smooth muscle differentiation." (PMID 39627614, 2025). "In the current study, KAT6B/A::KANSL1 uterine sarcomas falling into the core DNA methylation cluster were consistently histologically bland and showed no significant CNVs." (PMID 39392508, 2024). "In conclusion, KAT6B/A::KANSL1 uterine sarcoma is a molecularly unique type of uterine tumour that should be recognized as a distinct entity." (PMID 39392508, 2024). "Given the distinct global DNA methylation and gene expression profile, we advocate for KAT6B/A::KANSL1 uterine tumours to be recognized as a distinct type of uterine sarcoma—KAT6B/A::KANSL1 uterine sarcomas." (PMID 39392508, 2024). "In conclusion, KAT6B/A::KANSL1 uterine sarcoma is a molecularly unique tumour that should be recognized as a distinct entity." (PMID 39392508, 2024). "Perhaps surprisingly, in our study, KAT6B/A::KANSL1 uterine sarcomas with high-grade histological features exhibited a variable DNA methylation profile distinct from the core KAT6B/A::KANSL1 cluster tumours." (PMID 39392508, 2024). "This raises the question of whether secondary genomic alterations could play a role in high-grade transformation of KAT6B/A::KANSL1 uterine sarcomas, potentially correlating with an aggressive clinical course." (PMID 39392508, 2024).
uterine tumours (3 papers, 2023 to 2025). "Moreover, KAT6B/A::KANSL1 uterine tumours have demonstrated malignant potential with a risk for metastasis/recurrence despite typically bland cytomorphology and often a circumscribed tumour border." (PMID 39392508, 2024). "The second series included 12 KAT6B/A::KANSL1 uterine tumours (including 12 primary and 4 recurrent tumours)." (PMID 39392508, 2024). "For instance, if KAT6B/A::KANSL1 uterine tumours were to be considered a form of low-grade endometrial stromal neoplasm, the typically circumscribed tumour border would challenge our current diagnostic criteria that separate LGESS from ESN." (PMID 39392508, 2024). "Overall, studies to date have shown that KAT6B/A::KANSL1 uterine tumours can exhibit histologic and immunophenotypic features of both low-grade endometrial stromal and smooth muscle neoplasms." (PMID 39392508, 2024). "It is worth noting that while a significant subset of KAT6B/A::KANSL1 uterine tumours exhibits focal sex cord differentiation, they displayed a methylation profile that was also distinct from UTROSCTs." (PMID 39392508, 2024). "In this study we investigated DNA methylation patterns and copy number variations (CNVs) in a series of uterine tumours harboring KAT6B/A::KANSL1 gene fusions in comparison to other mesenchymal neoplasms of the gynecological tract." (PMID 39392508, 2024). "Herein we report the clinicopathologic and molecular features of a cohort of uterine tumours harbouring the KAT6B/A::KANSL1 gene fusion." (PMID 39392508, 2024). "As such, it is important to ascertain the nature and the precise classification of KAT6B/A::KANSL1 uterine tumours." (PMID 39392508, 2024). "In this study, we employed global DNA methylation profiling and CNV analyses to gain insights into the classification of KAT6B/A::KANSL1 uterine tumour in comparison to other uterine mesenchymal tumours." (PMID 39392508, 2024). "In addition, KAT6B/A::KANSL1 uterine tumours lack evidence of Wnt/β-catenin pathway activation that is typically seen in LGESS." (PMID 39392508, 2024). "The major novel finding of our study is that KAT6B/A::KANSL1 uterine tumours are defined by a specific DNA methylation signature that is distinct from other uterine mesenchymal neoplasms, indicating they constitute a distinct type of uterine mesenchymal tumour." (PMID 39392508, 2024).
Blepharophimosis (2 papers, 2018 to 2024). A fixed reduction in the vertical distance between the upper and lower eyelids with short palpebral fissures. "With the exception of KAT6B mutations identified in the SBBYS variant, and MED12 in an X-linked variant of Ohdo, the lack of known molecular causes has so far hampered more definitive classification of this broad group of blepharophimosis-ID syndromes." (PMID 29021403, 2018).
blepharophimosis mental retardation syndromes (2 papers, 2021 to 2024). "Because of the clinical overlapping and similarities, some researchers proposed that KAT6B causes two allelic GPS and SBBYS syndromes, whereas others have suggested them as two different disorders." (PMID 38178270, 2024).
colon cancer (2 papers, 2018 to 2021). "On the other hand, CIC, DST, KAT6B and NOTCH4 represent novel genes that may be implicated in the onset and/or development of colon cancer." (PMID 29844865, 2018). "On the other hand, CIC, DST, KAT6B and NOTCH4 have not been previously implicated in the development of colon cancer, and for this reason, deserve further studies." (PMID 29844865, 2018).
Kabuki syndrome (2 papers, 2021 to 2022). Kabuki syndrome (KS) is a multiple congenital anomaly syndrome characterized by typical facial features, skeletal anomalies, mild to moderate intellectual disability and postnatal growth deficiency. "A few of the chromatinopathies have previously been associated with CS: Kabuki syndrome, Bohring–Opitz syndrome (BOS), and two cases of KAT6B-related disorders." (PMID 33288889, 2021). "Other examples of genes with multiple signatures are SRCAP (Floating Harbor syndrome and DEHMBA), KMT2D (Kabuki syndrome and CHARGE-like phenotype) and KAT6B (GTPTS and SBBYSS)." (PMID 35860466, 2022).
leiomyosarcoma (2 papers, 2024 to 2025). An uncommon, aggressive malignant smooth muscle neoplasm, usually occurring in post-menopausal women. "RNA-sequencing-based gene expression profiling analysis showed a greater overlap of KAT6B::KANSL1 tumours with ESN and LGESS compared to leiomyomata and leiomyosarcoma." (PMID 39392508, 2024).
melanoma (2 papers, 2009 to 2022). A malignant, usually aggressive tumor composed of atypical, neoplastic melanocytes. "By performing survival analysis based on gene pair mutation, we observed that the mutation of nine gene pairs, such as “SERPINB3|RELN”, “KAT6B|RELN”, and “SERPINB3|PEG3”, were significantly correlated with patient survival in all four independent melanoma datasets (log-rank test p-value < 0.05)." (PMID 36139377, 2022).
non-small cell lung carcinoma (2 papers, 2022 to 2023). A group of at least three distinct histological types of lung cancer, including non-small cell squamous cell carcinoma, adenocarcinoma, and large cell carcinoma. "Similarly, Kat6b plays a tumor suppressor role in non-small-cell lung cancer wherein its loss leads to cancer growth." (PMID 37958378, 2023). "Six transcription factors (E2F3, FHL2, ETS1, KAT6B, TWIST1, and RUNX2) were identified in the GRN as essential regulators of gene expression in non-small-cell lung cancer (NSCLC) and related to the lung tumoral process." (PMID 36551878, 2022).
RASopathy (2 papers, 2021 to 2022). "However, alterations in KAT6B are also observed in several other developmental disorders with features similar to those of the RASopathies, including Say-Barber-Biesecker-Young-Simpson syndrome (OMIM 603736), so further validation is needed." (PMID 35178568, 2022).
tongue cancer (2 papers, 2018 to 2023). A malignant neoplasm affecting the tongue. "Given the regulatory relationship between miR-22 and KAT6B identified in our cell culture studies, we focused whether the miR-22/KAT6B might associate with the prognosis of tongue cancer patients." (PMID 30041677, 2018). "Previously, we demonstrated that miR‐22 (miR‐22‐3p) post‐transcriptionally regulated KAT6B expression in tongue cancer cells." (PMID 36639835, 2023). "We also detected activation of miR‐22/lncRNA/KAT6B/NF‐κB signalling in recurrent cancers compared to paired primary tongue cancers." (PMID 36639835, 2023). "Our present study shows that miR-22 sensitizes primary tongue cancer cells to CDDP by targeting KAT6B expression." (PMID 30041677, 2018). "The expression levels of miR-22 and KAT6B were evaluated in clinical samples of tongue cancer patients by Q-PCR." (PMID 30041677, 2018). "In this study, ectopic overexpression of miR‐22 inhibited KAT6B expression in tongue cancer cells." (PMID 36639835, 2023). "Given that NF‐κB signalling was regulated by KAT6B in tongue cancer cells, we wondered whether KAT6B was also involved in the activation of NF‐κB signalling stimulated by dying cells." (PMID 36639835, 2023). "Collectively, these data indicate that the chemo-sensitizing effect of miR-22 in tongue cancer may depend on KAT6B downregulation." (PMID 30041677, 2018). "The increased chemosensitivity could be mediated by miR-22-dependent downregulation of KAT6B, resulting in inhibited NF-kB activity and increased apoptosis upon chemotherapy in tongue cancer cells." (PMID 30041677, 2018). "Furthermore, we found that KAT6B levels in primary tumors of tongue cancer patients were inversely correlated with miR-22 expression, and the high expression of KAT6B was associated with poor prognosis." (PMID 30041677, 2018).
22q11.2 deletion syndrome (1 paper, 2025). 22q11.2 deletion syndrome (DS) is a chromosomal anomaly which causes a congenital malformation disorder whose common features include cardiac defects, palatal anomalies, facial dysmorphism, developmental delay and immune deficiency. "Differential diagnosis encompasses other chromosomal deletions such as 22q11.2 deletion syndrome and other pathogenic variants such as lysine acetyltransferase 6B (KAT6B) and lysine acetyltransferase 8 (KAT8)." (PMID 40115715, 2025).
adenoma (1 paper, 2023). A neoplasm arising from the epithelium.